HLA-DRB1 (major histocompatibility complex, class II, DR beta 1)
Diseases named in the same sentence as HLA-DRB1 in open-access papers (continued):
Sharing a sentence is not in itself a finding about the gene and the disease.
pemphigus (8 papers, 2012 to 2025). Pemphigus is a group of rare autoimmune diseases that cause blistering of the skin and mucous membranes (mouth, nose, throat, eyes, and genitals).This conditioncan occur at any age, but often strikes people in middle or older age. "An interaction between genetic predisposition (HLA-DRB1) and environmental factors has been documented in post-medication pemphigus." (PMID 40098967, 2025). "Further positive associations after exclusion of pemphigus were observed in HLA-DRB1*11, *12, *15 and *16." (PMID 35654912, 2022). "The negative associations were less pronounced, and after exclusion of pemphigus, only HLA-DRB1*13 was found at reduced frequency (genotype: OR 0.41; 95% CI 0.28–0.61; p < 0.00001, allele: OR: 0.49, 95% CI 0.20–1.21, p = 0.12)." (PMID 35654912, 2022). "There was substantial heterogeneity for most of the alleles with the exception of HLA-DRB1*14, which showed a low level of heterogeneity only in the pemphigus allele frequency, but was highly heterogenic otherwise." (PMID 35654912, 2022). "Previous studies have shown that it is associated with susceptibility to insulin autoimmune syndrome, silicosis, prostate cancer, and pemphigus in Asian ancestry populations, which implied that HLA-DRB1*0406 is a risk allele for immune dysfunction diseases." (PMID 23139797, 2012). "HLA-DRB1*11 and 15 were also positively associated with IgG4-AID after exclusion of pemphigus (in addition to HLA-DRB1*12 and 16), these could play a role in a different subset of patients, perhaps in neurological IgG4-AID." (PMID 35654912, 2022). "Furthermore, human leukocyte antigen (HLA) molecules, including alleles HLA-DQB1*0503 and HLA-DRB1*0402 in pemphigus, as well as HLA-DQB1*0301 in pemphigoid, may represent key predisposing factors for drug-induced AIBDs." (PMID 38793716, 2024). "In this rare form of pemphigus, there is no consensus on the mechanism of pathogenesis, but an interaction between genetic predisposition (HLA-DRB1) and environmental factors has been documented." (PMID 40098967, 2025). "Data of 15 HLA-DRB1 alleles (DRB1*01–16) and five HLA-DQB1 alleles (DQB1*02–06) could be extracted from studies on pemphigus, MuSK MG and TTP." (PMID 35654912, 2022). "Interestingly, while MuSK MG and pemphigus seem to have very similar genetic associations, TTP showed opposite effects for several alleles, and in HLA-DRB1*04 and HLA-DRB1*11 these were significant." (PMID 35654912, 2022). "While we could confirm the positive association with HLA-DRB1*14, HLA-DQB1*05 and the HLA-DRB1*14-DQB1*05 haplotype after exclusion of pemphigus patients, the frequency of HLA-DRB1*04 was significantly decreased, suggesting this association is specific for pemphigus." (PMID 35654912, 2022). "Since there was a predominance of pemphigus studies (37/52 studies), we re-analyzed the data after exclusion of the pemphigus studies and could reproduce the associations with the HLA-DRB1*13, HLA-DRB1*14 and HLA-DQB1*05 alleles and the HLA-DRB1*14-DQB1*05 haplotype." (PMID 35654912, 2022). "Increased frequencies of HLA-DRB1*04 and HLA-DRB1*14 and decreased frequencies of HLA-DRB1*03, HLA-DRB1*07 and HLA-DRB1*15 were observed in the pemphigus patients." (PMID 35654912, 2022). "HLA-DRB1*13 showed low heterogeneity in TTP and IgG4-AID excluding pemphigus, but moderate heterogeneity in all IgG4 AID collectively." (PMID 35654912, 2022). "There is a trend toward increased frequency of HLA-DQB1*05:02 in countries with lower latitude, such as Italy, which also show increased frequency of MuSK MG and pemphigus, while there is a reduced frequency for HLA-DRB1*04 and no apparent change in HLA-DRB1*14 in countries with low latitudes." (PMID 33584677, 2020).
polyarthritis (8 papers, 2012 to 2025). "In the subtype-specific association analysis, an increased risk associated with HLA-DRB1*08:01 was largely attributable to the subtypes oligoarthritis (OR = 4.98, 95% CI: 3.22–7.70) and RF-negative polyarthritis (OR = 4.5, 95% CI: 2.62–7.72)." (PMID 39187888, 2024). "Examination of the genotypes of JIA patients by PCR-sequence-specific oligonucleotide probe methodology has shown that HLA-DRB1*04:05 is associated with polyarthritis RF-positive." (PMID 33076506, 2020). "Only one single RF-positive polyarthritis patient and one ERA patient were positive for HLA-DRB1*11 alleles (the difference was only statistically significant in ERA subtype, P = 0.02)." (PMID 39187888, 2024). "HLA-DRB1*04 is associated with Rheumathoid Factor (RF)-positive polyarthritis in children and RF-positive RA in adults, whereas HLA-DRB1*08, HLA-DRB1*11, and HLA-DRB1*13 are strongest associated with RF-negative polyarthritis and oligoarticular JIA." (PMID 35967305, 2022). "HLA-DRB1 amino acid position 13 showed the strongest connection with oligoarthritis and both RF-positive and RF-negative polyarthritis." (PMID 33076506, 2020). "JIA patients (39 oligoarthritis, 48 RF-positive polyarthritis, 19 RF-negative polyarthritis and 82 systemic) and 188 healthy controls were genotyped for HLA-DRB1 by PCR-sequence-specific oligonucleotide probe methodology." (PMID 28182665, 2017). "Positive rheumatoid factor polyarthritis has been associated with HLA-DR4 and HLA-DRB1*11; negative rheumatoid factor polyarthritis has been demonstrated to be associated with HLA-DRB1*08 and HLA-DPB1*03." (PMID 23133455, 2012).
lung disease (7 papers, 2014 to 2024). "Several HLA genes have been linked to a predisposition to RA-related lung diseases, such as HLA-DQB1*03:01, HLA-DRB1*15, and HLA-DRB1*16, as well as specific mutations in other genes, such as SFTPC, RTEL1, and TERT." (PMID 37238933, 2023). "Both HLA-DRB1*04 and HLA-DRB1*12 alleles are likely linked to the lung disease (p = 0.01, pcorr NS; OR = 2.82; 95% CI: 1.15–6.76 and p = 0.02, pcorr NS; OR = 2.52; 95% CI: 1.02–6.07, respectively)." (PMID 24894810, 2014). "Thus, OC43 pre-exposure for 16 days was sufficient to elicit a cross-protective response against SARS-CoV-2 infection and lung disease in HLA-DRB1*0101 Ifnar1−/− mice." (PMID 38278784, 2024). "Given that clinical studies targeting the systemic IL-33 signaling pathway are currently underway in the treatment of COPD (clinicaltrials.gov; NCT04701983; NCT03615040), investigating the role of IL-33 in HLA-DRB1+ RA and lung diseases resulting from airborne exposures may be warranted." (PMID 35717175, 2022). "The patient who had a reaction to anakinra was negative for HLA-DRB1*15 and he did not develop lung disease (3 years follow-up)." (PMID 37848930, 2023).
narcolepsy (7 papers, 2008 to 2024). A sleep disorder characterized by a tendency for excessive sleepiness during the day which occurs even after adequate sleep in the nighttime. "SNP rs5770917 located between CPT1B and CHKB, and HLA-DRB1*1501-DQB1*0602 haplotype were previously identified as susceptibility loci for narcolepsy with cataplexy." (PMID 19404393, 2009). "HLA-DRB1*1501 (OR = 8.2; pc < 0.0001) and DQB1*0602 (OR = 8.4; pc < 0.0001) were found positively associated with narcolepsy." (PMID 18706091, 2008). "HLA-DRB1, DQA1, and DQB1 are vulnerable genes associated with autoimmune diseases such as Graves’ disease, rheumatoid arthritis, type I diabetes, and narcolepsy." (PMID 36358399, 2022). "HLA-DRB1 distribution in Mexican Mestizo patients with narcolepsy and in healthy controls." (PMID 18706091, 2008).
pemphigus vulgaris (7 papers, 2012 to 2023). Pemphigus is a group of chronic autoimmune skin diseases characterized by blister formations on the outer layer of the skin and the mucous membranes. "Amino acid positions in HLA-DRB1 alleles associated with pemphigus vulgaris in the Bulgarian population." (PMID 35983062, 2022). "Various alleles of the HLA-DRB1 gene have been associated with pemphigus vulgaris (PV), but studies of these genes have been largely carried out in small populations and the results from different studies have not been consistent." (PMID 22564118, 2012). "MuSK myasthenia gravis patients with HLA-DRB1*14 presented with increased serum levels of IgG4 autoantibodies and IL-10 concentrations, and IL-10 also plays a role in animal models of pemphigus vulgaris and MuSK myasthenia gravis." (PMID 35095860, 2021). "Different alleles, HLA-DRB1*04:04,14:02 and 14:06 all share a sequence in the hypervariable region in residues 67 to 74 (LLEQRRAA) and these alleles were reported to be linked to fogo selvagem, an endemic form of pemphigus vulgaris." (PMID 33584677, 2020).
pulmonary sarcoidosis (7 papers, 2010 to 2025). Sarcoidosis affecting the lung parenchyma. "The distributions of the HLA-DRB1 alleles were significantly different between the pulmonary sarcoidosis patients and the EPS patients (P < 0.001)." (PMID 25866481, 2015). "This study shows also a significant difference between the overall distribution of the HLA-DRB1 alleles between pulmonary sarcoidosis patients and patients with EPS." (PMID 25866481, 2015). "In pulmonary sarcoidosis, patients carrying the HLA-DRB1*0301 allele have shown more AV2S3 positive T-cells, but less regulatory T-cells than those carrying other HLA-DRB1 alleles." (PMID 23139797, 2012). "While this study specifically focused on this phenomenon in pulmonary sarcoidosis, analogous studies are required in order to determine whether this trend holds true for HLA-DRB1*03+ patients with other inflammatory diseases." (PMID 30038611, 2018). "Previous studies revealed that HLA-DRB1*1501 and HLA-DRB1*0602 are correlated with a chronic course, while HLA-DRB1*150101 and HLA-DRB1*0602 are related to severe pulmonary sarcoidosis." (PMID 39904950, 2025).
Sjögren’s syndrome (7 papers, 2010 to 2025). "Ser57 of HLA-DRB1, which was associated with GD in our data, has been reported to be associated with Primary Sjogren's syndrome in a Chinese study." (PMID 31091281, 2019).
agranulocytosis (6 papers, 2017 to 2025). "For example, two alleles, HLA-B*38:02 and HLA-DRB1*08:03, are strongly associated with the adverse side effect of induced agranulocytosis when starting anti-thyroid medication." (PMID 37033561, 2023). "HLA-B*27:05 (P = 1.10 × 10−4), HLA-B*38:02 (P = 2.41 × 10−4) and HLA-DRB1*08:03(P = 1.57 × 10−3) were significantly associated with ATD-induced agranulocytosis after adjusting with Bonferroni’s correction (P < 3.57 × 10−3)." (PMID 28931918, 2017). "HLA-B*27:05 (P = 1.10 × 10−4), HLA-B*38:02 (P = 2.41 × 10−4) and HLA-DRB1*08:03 (P = 1.57 × 10−3) were susceptibility HLA variants for ATD-induced agranulocytosis." (PMID 28931918, 2017). "The associations of HLA-B*27:05, HLA-DRB1*08:03 and 5 SNPs (rs2596487, rs116869525, rs2228391, rs1811197 and rs4349859) with agranulocytosis were still significant in the female patients." (PMID 28931918, 2017). "HLA-DRB1*08:03 was recently shown to contribute to the risk of ATD-induced agranulocytosis in Japanese and Taiwan Chinese populations." (PMID 28931918, 2017). "Our findings support the association between genetic variations of HLA-B and HLA-DRB1 with ATD-induced agranulocytosis in a Han population from northern China." (PMID 28931918, 2017). "When we considered medication type (MMI or PTU), the associations of two HLA alleles (HLA-B*38:02 and HLA-DRB1*08:03) and 2 SNPs (rs2596487 and rs1811197) with agranulocytosis were strengthened when patients with PTU-induced agranulocytosis were removed from the analysis." (PMID 28931918, 2017). "Certain HLA alleles, such as HLA-DRB1*04:02, HLA-DPB1*05:02, HLA-DQB1 (126Q), HLA-B (158T), and HLA-B*59:01, have been reported to be associated with clozapine-induced agranulocytosis." (PMID 38516266, 2024). "HLA-DRB1*08:03 was present in 29.6% of patients with agranulocytosis but was only present in 8.9% of controls with GD with an OR of 4.316 (95% CI = 1.56–11.93) for allele carriers compared with non-carriers." (PMID 28931918, 2017). "Second, rs116869525, which was in high LD with HLA-DRB1*08:03 in both Chinese patients from Taiwan21 and our population, showed an association with ATD-induced agranulocytosis in both populations." (PMID 28931918, 2017). "In conclusion, HLA-B*27:05, HLA-B*38:02, HLA-DRB1 *08:03 and other SNPs within chromosome 6 are associated with the susceptibility of a Chinese Han population from northern China to ATD-induced agranulocytosis." (PMID 28931918, 2017). "Our findings are in line with the Hong Kong GWAS that the associations of HLA-B*38:02, HLA-DRB1*08:03, rs2596487 and rs1811197 with ATD-induced agranulocytosis become even stronger in patients with agranulocytosis caused only by MMI." (PMID 28931918, 2017). "Another 4 HLA alleles (HLA-B*38:02, HLA-B*27:05, HLA-DRB1*01:01 and HLA-DRB1*04:02) with frequencies less than 5% were also included in the analysis because of significant associations with drug-induced agranulocytosis that have been reported in the literatures." (PMID 28931918, 2017). "Neither of the 2 PTU-induced agranulocytosis cases carried HLA-B*38:02 or HLA-DRB1*08:03." (PMID 28931918, 2017).
Behçet's disease (6 papers, 2013 to 2024). "Our research highlights specific HLA associations in Behçet's disease (BD), particularly the significant relation of HLA-DRB1*14:54:01 with ocular manifestations." (PMID 38575661, 2024).
dengue (6 papers, 2008 to 2025). "In contrast, HLA-DRB1*03 and HLA-DRB1*09 were linked with reduced risk of severe dengue, highlighting its potential protective role." (PMID 40740782, 2025). "On the other hand, HLA-B alleles 35:01 and 51:01 and HLA-DRB1* 12:02 were associated with a higher risk of developing severe dengue compared to the background population." (PMID 25659158, 2015). "The HLA-B alleles 07:05, 38:02 and 58:01 and HLA-DRB1* 03:01 were also reduced in the severe dengue group compared to the population background group, but these were not statistically significant after correction." (PMID 25659158, 2015). "The same goes for the HLA-DRB1*0401 or -DRB1*0802 class II alleles, which are associated with an increased resistance or susceptibility to severe dengue disease, respectively, and the phenotype of responding cytotoxic CD4 T cells." (PMID 29473899, 2018). "Two HLA Class II alleles, HLA-DRB1*03:01 and DRB1*12:02, were also associated with dengue in our study population, although the significance was lost after correction." (PMID 25659158, 2015). "When HLA-A*33:01 was analyzed for linkage disequilibrium with alleles in other loci found in this study to have a similar tendency in dengue patients (i.e., protection against severe dengue), we found that HLA-B*58:01 and HLA-DRB1*03:01 are in linkage disequilibrium with A*33:01 (data not shown)." (PMID 25659158, 2015).
depression (6 papers, 2016 to 2025). "The allele with strongest evidence for association with depression was HLA-B*08:01, followed by HLA-DQB1*02:01 and HLA-DRB1*03:01." (PMID 31570195, 2020).
IgA vasculitis (6 papers, 2015 to 2024). "Studies concerning the genetic background of IgA vasculitis (IgAV), a small-vessel vasculitis occurring predominantly in childhood, have confirmed that the HLA-DRB1 gene showed a strong association with disease susceptibility." (PMID 38255953, 2024). "They found a statistically significant increase in the HLA-B*41:02 allele in patients with IgA vasculitis when compared with controls, which was independent of the previously reported association with the HLA-DRB1*01 allele." (PMID 34299162, 2021).
primary biliary cholangitis (6 papers, 2013 to 2024). Primary biliary cholangitis (PBC) is a chronic and slowly progressive cholestatic liver disease of autoimmune etiology characterized by injury of the intrahepatic bile ducts that may eventually lead to liver failure. "In addition, two studies of large populations have independently found that AOAH mRNA expression is associated in trans with polymorphisms in HLA-DRB1 that, in turn, have been strongly linked to colitis and primary biliary cirrhosis." (PMID 23675296, 2013).
Sepsis (6 papers, 2012 to 2025). Sepsis is defined as life-threatening organ dysfunction caused by a dysregulated host response to infection. "In detail, transcription of genes encoding for HLA-DR subunits (HLA-DRA and HLA-DRB1) was strongly reduced in patients with postoperative sepsis (****p<0.0001 and ***p<0.001)." (PMID 33939725, 2021). "In detail, genes encoding for subunits of HLA-DR (HLA-DRA and HLA-DRB1) showed a lower expression in patients with HLA-DR suppressive sepsis (**p<0.01 and *p<0.05)." (PMID 30212590, 2018). "The partition of HLA-DRB1 alleles was similar in this cohort with severe sepsis and septic shock compared to the reference population." (PMID 22701553, 2012). "Gene expression analysis revealed a sepsis-associated decreased transcription of (i) the classical HLA genes HLA-DRA, HLA-DRB1, HLA-DPA1 and HLA-DPB1 and (ii) the gene of the MHC-II master regulator, CIITA (Class II Major Histocompatibility Complex Transactivator)." (PMID 33939725, 2021). "As an important finding, these interactions were confirmed for pairs of CTCF-sites and promoter regions of genes, which also displayed sepsis-induced alterations in our study (CM1 and HLA-DRA, CM2 and HLA-DRB1, CM9 and HLA-DPA1 and CM9 and HLA-DB1)." (PMID 33939725, 2021). "Similar to T cells and NK cells in sepsis, both naïve and switched resting B cell populations display significant decreases in the expression of several MHC-class II genes, including HLA-DRA, HLA-DRB1, HLA-DMA and HLA-DPA1." (PMID 41208955, 2025). "Additional experiments revealed that the observed elevation in CTCF expression, CTCF binding at CM1, CM2, CM3 and CM9 as well as the reduced expression of adjacent classical HLA genes HLA-DRA, HLA-DRB1, HLA-DPA1 and HLA-DPB1 persisted in all patients with postoperative sepsis." (PMID 33939725, 2021). "Even more importantly, the observed reduction in classical HLA-DRA, HLA-DRB1, HLA-DPA1 and HLA-DPB1 transcription as well as the decline in monocyte HLA-DR surface expression persisted in all patients with postoperative sepsis despite a recovery of CIITA transcription levels during the study period." (PMID 33939725, 2021).
acute lymphoblastic leukemia (5 papers, 2016 to 2025). Leukemia with an acute onset, characterized by the presence of lymphoblasts in the bone marrow and the peripheral blood. "The HLA-DRB1*11 and HLA-A*32 alleles are particularly noteworthy for their possible predictive importance in juvenile acute lymphoblastic leukemia (ALL)." (PMID 40508101, 2025). "A recent study found the HLA-DRB1*07 and HLA-DRB1*12 alleles to be protective factors in patients with acute lymphoblastic leukemia (ALL)." (PMID 40508101, 2025). "An Egyptian investigation revealed that the HLA-DRB1*04 allele may serve as a female-specific susceptibility factor for pediatric acute lymphoblastic leukemia (ALL) and could affect the age of onset." (PMID 40508101, 2025). "As for the role of HLA-DRB1*11:04:01 in disease occurrence, evidence suggests its implication in acute lymphoblastic leukemia (ALL) and hairy cell leukemia, with hemolytic uremic syndrome." (PMID 39329950, 2024). "However, most patients evaluated by Schaap and coworkers were diagnosed with acute lymphoblastic leukemia (ALL), donors were HLA-A, HLA-B, HLA-DRB1, and HLA-DQB1-identical siblings, and all patients who were evaluated received TCD grafts." (PMID 34950586, 2021).